OR4K13 (olfactory receptor family 4 subfamily K member 13)
Description:
Odorant receptor.
Synonyms: OR14-27
Tractability: Antibody: UniProt places it where antibodies can reach, with medium confidence; UniProt predicts a signal peptide or a membrane-spanning region; its Gene Ontology location is reachable by antibodies, with medium confidence.
Gene: Protein-coding gene on chromosome 14 (20,029,399 to 20,036,038, reverse strand). Ensembl gene ENSG00000176253.
Subcellular location: Cell membrane
Pathways (Reactome):
Sensory Perception: Expression and translocation of olfactory receptors
Gene Ontology:
Molecular function: olfactory receptor activity; G protein-coupled receptor activity
Biological process: detection of chemical stimulus involved in sensory perception of smell; G protein-coupled receptor signaling pathway
Cellular component: plasma membrane; membrane
Genetic constraint (gnomAD): Missense variants: 367 observed, 347.42 expected, observed/expected ratio (o/e) 1.06, 90% interval 0.97 to 1.15. Synonymous variants: 149 observed, 128.4 expected, observed/expected ratio (o/e) 1.16, 90% interval 1.01 to 1.33.
Homologues: Orthologues: chimpanzee OR4K13 (99% identical), macaque OR4K13 (95% identical), pig OR4K13 (89% identical). Paralogues in human: OR4K14 (67% identical), OR4K15 (67% identical), OR4K1 (62% identical), OR4L1 (61% identical), OR4K5 (60% identical), OR4K17 (59% identical), OR4K2 (58% identical), OR4F5 (58% identical), OR4F4 (57% identical), OR4F17 (57% identical), OR4F6 (53% identical), OR4F16 (52% identical), and 116 more.
Diseases named in the same sentence as OR4K13 in open-access papers:
OR4K13 is named in the same sentence as 1 disease in open-access papers, as found by Europe PMC text mining. Sharing a sentence is not in itself a finding about the gene and the disease.
OR4K13 shares sentences with these, for which no sentence is quoted: bipolar disorder (1 paper).